CSF2RBP1 (CSF2RB pseudogene 1)
Synonyms: CSF2RB2; fF45C1.2
Gene: Transcribed unprocessed pseudogene on chromosome 22 (36,950,529 to 36,953,723, reverse strand). Ensembl gene ENSG00000232254.
Diseases named in the same sentence as CSF2RBP1 in open-access papers:
CSF2RBP1 is named in the same sentence as 8 diseases in open-access papers, as found by Europe PMC text mining. Sharing a sentence is not in itself a finding about the gene and the disease.
CSF2RBP1 shares sentences with these, for which no sentence is quoted: cancer (2 papers); infection (2); Arthritis (1); breast carcinoma (1); breast tumors (1); Cachexia (1); colitis (1); experimental autoimmune encephalomyelitis (1).